MID1IP1 (MID1 interacting protein 1)
Description:
Plays a role in the regulation of lipogenesis in liver. Up-regulates ACACA enzyme activity. Required for efficient lipid biosynthesis, including triacylglycerol, diacylglycerol and phospholipid. Involved in stabilization of microtubules (By similarity).
Synonyms: S14R; MIG12; STRAIT11499; FLJ10386; THRSPL; G12-like
Tractability: PROTAC: ubiquitination databases record sites on it; its protein half-life has been measured.
Gene: Protein-coding gene on chromosome X (38,801,417 to 38,806,537, forward strand). Ensembl gene ENSG00000165175.
Subcellular location: Nucleus; Cytoplasm; Cytoplasm, cytoskeleton
Pathways (Reactome):
Metabolism: Carnitine shuttle
Gene Ontology:
Molecular function: protein binding; enzyme activator activity; identical protein binding
Biological process: negative regulation of microtubule depolymerization; positive regulation of fatty acid biosynthetic process; positive regulation of ligase activity; protein polymerization; regulation of lipid biosynthetic process
Cellular component: cytosol; microtubule cytoskeleton; nucleus; cytoplasm; cytoskeleton
Homologues: Orthologues: chimpanzee MID1IP1 (100% identical), macaque MID1IP1 (100% identical), pig MID1IP1 (95% identical), rabbit MID1IP1 (94% identical), dog MID1IP1 (93% identical), rat Mid1ip1 (89% identical), mouse Mid1ip1 (88% identical), guinea pig MID1IP1 (64% identical), tropical clawed frog mid1ip1 (58% identical), zebrafish mid1ip1a (43% identical), Drosophila melanogaster CG2765 (22% identical). Paralogues in human: THRSP (29% identical).
Diseases named in the same sentence as MID1IP1 in open-access papers:
MID1IP1 is named in the same sentence as 13 diseases in open-access papers, as found by Europe PMC text mining. Sharing a sentence is not in itself a finding about the gene and the disease. The quoted sentences say what the papers report.
colorectal cancer (7 papers, 2020 to 2025). A primary or metastatic malignant neoplasm that affects the colon or rectum. "CNOT2, MID1IP1, and Pin1 genes are overexpressed in cancer cells of various organs, such as colorectal cancer and liver cancer, promoting tumor growth and metastasis, and commonly regulating the expression of c-Myc." (PMID 36569330, 2022). "Our results indicate that TA3 suppresses the expression of c-Myc via downregulation of CNOT2 and MID1IP1 in colorectal cancer cell lines, thereby inducing apoptotic markers." (PMID 36233202, 2022). "Therefore, this study focused on controlling the expression of c-Myc in various colorectal cancer cells, and further, an experiment was conducted focusing only on tumor genes c-Myc, MID1IP1, and CNOT2 using HCT116p53+/+." (PMID 36233202, 2022). "MID1IP1 overexpression activates c-Myc, and inhibition of CNOT2 enhances its antitumor effect by inducing apoptosis in colorectal cancer cells through MID1IP1." (PMID 37110707, 2023). "Building upon these findings, we targeted c-Myc in colorectal cancer cells using CS&Z, and accordingly detected a reduction in c-Myc protein levels, which was accompanied by apoptotic changes in the protein levels of PARP, caspase 3, CNOT2, and MID1IP1." (PMID 40429805, 2025). "In addition, it has been reported that the simultaneous knockdown of MID1IP1 and CNOT2 in the liver and in colorectal cancer cells further downregulates c-Myc, thereby contributing to cancer cell growth and apoptosis." (PMID 36233202, 2022). "Furthermore, CNOT2 knockdown enhanced the inhibitory effect of MID1IP1 depletion on c-Myc and pro-PARP, even in HCT116 colorectal cancer cells." (PMID 32316188, 2020). "Moreover, a follow-up study is planned to further investigate the anti-cancer mechanism of TA3 in colorectal cancer in relation to whether TA3 binds directly to CNOT2 and MID1IP1 to interfere with expression." (PMID 36233202, 2022). "Furthermore, based on previous research, we established that the inhibition of CNOT2 induces apoptosis via reductions in MID1IP1 and c-Myc, and we thus investigated whether CS&Z regulates the expression of the oncogenes MID1IP1 and CNOT2 in colorectal cancer cells." (PMID 40429805, 2025).
liver cancer (7 papers, 2020 to 2025). An epithelial or non-epithelial malignant neoplasm that arises from the liver. "In hepatocellular carcinoma cell lines (HepG2 and Huh7), CNOT2 deficiency was found to enhance the antitumor effects of MID1IP1 depletion while reducing apoptosis markers, suggesting a functional interplay between CNOT2 and MID1IP1 in liver cancer cells." (PMID 40864769, 2025). "We also previously reported that the simultaneous knockdown of CNOT2 and MID1IP1 in colorectal and liver cancer cells contributes to cancer cell growth and apoptosis by significantly inhibiting c-Myc expression." (PMID 36569330, 2022). "It has recently been reported that MID1IP1 is present upstream of AMP-activated protein kinase (AMPK) in liver cancer cells and is a negative regulator of AMPK." (PMID 36233202, 2022). "Our previous studies show that MID1IP1 regulates liver cancer growth through c-Myc mediated by ribosomal protein L5 (RPL5) and L11 (RPL11)." (PMID 34680125, 2021). "Taken together, these findings provide novel insight that MID1IP1 promotes the growth of liver cancer via colocalization with c-Myc mediated by ribosomal protein L5 and L11 and CNOT2 as a potent oncogenic molecule." (PMID 32316188, 2020). "Overall, these findings suggest that MID1IP1 promotes liver cancer progression via colocalization with c-Myc mediated by ribosomal protein L5 and L11 and CNOT2 as a potent oncogenic molecule." (PMID 32316188, 2020). "Overall, these findings provide novel insight that MID1IP1 promotes the growth of liver cancer via colocalization with c-Myc mediated by ribosomal proteins L5 and L11 and CNOT2 as a potent oncogenic molecule." (PMID 32316188, 2020). "Our previous paper showed that CNOT2 regulates liver cancer cell growth through c-Myc and MID1IP1." (PMID 36569330, 2022). "Furthermore, CNOT2 is related to c-Myc, which is mediated by the ribosomal proteins L5, L11, or by midline 1 interacting protein 1 (MID1IP1) in liver cancer cells." (PMID 34680125, 2021). "Furthermore, depletion of CNOT2 was shown to enhance the antitumor effect of midline 1 interacting protein 1 (MID1IP1) depletion, thus inhibiting c-Myc expression in liver cancer cells." (PMID 34680125, 2021). "Furthermore, MID1IP1 regulates liver cancer growth through c-Myc mediated by CNOT2." (PMID 36233202, 2022). "In liver cancer, RPL11-mediated MID1 interacting protein 1 depletion reduced cell viability and colony formation by inhibiting MYC gene expression." (PMID 36869281, 2023). "MID1IP1 supports the cooperation of proto-oncogene c-Myc, mediated by RPL5, RPL11, and CNOT2, which acts as a potent oncogene molecule, in the progression of liver cancer." (PMID 40864769, 2025).
colon cancer (5 papers, 2022 to 2023). "We identified changes in protein expression levels of oncogenes such as CNOT2 and MID1IP1 when ES was treated in colon cancer cells through Western blotting." (PMID 37110707, 2023). "Combination treatment also increased apoptosis and further reduced expression of the oncogenes c-Myc, CNOT2, and MID1IP1 in colon cancer cells." (PMID 38139419, 2023). "TSAIII can induce colon cancer HCT116 cell apoptosis by suppressing the expression of MID1IP1, CNOT2, and c-Myc, interrupting the interaction between MID1IP1 and c-Myc and decreasing the stability of c-Myc." (PMID 37513375, 2023). "In this study, we confirmed that ACN induces apoptosis by negatively regulating oncogenes, including c-Myc, CNOT2, and MID1IP1, in various colon cancer cells." (PMID 38139419, 2023). "In addition, Western blotting demonstrated that the expression of MID1IP1 was reduced when the colon cancer cells were treated with ES." (PMID 37110707, 2023). "Therefore, we confirm that ES has anticancer effects by inducing apoptotic cell death and regulating the oncogenes CNOT2 and MID1IP1, suggesting its potential for use in the treatment of colon cancer." (PMID 37110707, 2023). "Thus, to the best of our knowledge, this study is the first to reveal that TA3-induced apoptosis through c-Myc requires CNOT2 or MID1IP1 in colon cancer cells." (PMID 36233202, 2022). "The protein expression of c-Myc, CNOT2, and MID1IP1 decreased in a dose- and time-dependent manner after ACN treatment of colon cancer cells." (PMID 38139419, 2023). "Altogether, our results reveal a mechanism by which TA3 induces apoptosis through inhibiting c-Myc expression via CNOT2 or MID1IP1 in HCT116, which may help in the development of new therapies for colon cancer based on TA3 in the future." (PMID 36233202, 2022). "MID1IP1 is an oncogene well-known as a negative regulator of AMP-activated protein kinase (AMPK), and our recent study has shown that knockdown of MID1IP1 can inhibit the expression of c-Myc in the growth of liver and colon cancer." (PMID 36569330, 2022).
fatty liver (2 papers, 2019 to 2022). "MID1IP1 was associated with the synthesis of fatty acid, which promote the risk of fatty liver diseases." (PMID 36558373, 2022). "Taken together, our findings suggest that shikimic acid has hypolipogenic effect in HepG2 and 3T3-L1 cells via phosphorylation of AMPK/ACC and inhibition of MID1IP1 as a potent candidate for prevention or treatment of fatty liver and hyperlipidemia." (PMID 30700011, 2019). "Shikimic acid has hypolipogenic effect in HepG2 and 3T3-L1 cells via phosphorylation of AMPK/ACC and inhibition of MID1IP1 as a potent candidate for prevention or treatment of fatty liver and hyperlipidemia." (PMID 30700011, 2019). "Overall, our findings provide evidence that shikimic acid has a hypolipogenic effect in HepG2 and 3T3-L1 cells via phosphorylation of AMPK/ACC and inhibition of MID1IP1 as a potential candidate for prevention or treatment of fatty liver and hyperlipidemia." (PMID 30700011, 2019).
hepatocellular carcinoma (2 papers, 2019 to 2025). A malignant tumor that arises from hepatocytes. "Thus, in the present study, hypolipogenic mechanism of shikimic acid was elucidated in HepG2 and Huh7 hepatocellular carcinoma HCC cells and 3T3-L1 adipocytes in association with AMPK/ACC and MID1IP1 signaling axis." (PMID 30700011, 2019). "Furthermore, researchers studied the oncogenic potential of MID1IP1 in hepatocellular carcinoma cell (HCC) growth in relation to ribosomal protein L5 and L11 and CNOT2-mediated c-Myc signaling and found that CNOT2 knockdown could further inhibit the downregulation of MID1IP1 by c-Myc." (PMID 40864769, 2025).
hydronephrosis (1 paper, 2024). Collection of urine in the renal pelvis that results in dilatation of the renal pelvis and calyces. "Our data showed that in Tspan7 transgenic mice exhibiting a hydronephrosis-like pathology, not only Otc, the gene most adjacent to Tspan7, but also other contiguous genes, Xk, Dynlt3, and Mid1ip1, were affected." (PMID 39000307, 2024).
lipid metabolic disorder (1 paper, 2022). "Additionally, three genes associated with lipid metabolism (Angptl8, Gadd45a, and Mid1ip1) are significantly downregulated in CD19−/− mice, providing further support for our argument that CD19−/− mice develop a lipid metabolic disorder." (PMID 35082296, 2022).
cancer (9 papers, 2019 to 2025). A tumor composed of atypical neoplastic, often pleomorphic cells that invade other tissues. "CNOT2 is associated with MID1IP1 in the regulation of c-Myc expression and the induction of apoptosis in cancer cells." (PMID 38139419, 2023). "Previous studies have revealed that CNOT2 is related to MID1IP1, which is associated with the regulation of c-Myc expression and apoptosis in cancer cells, and that CNOT2 knockdown induces apoptosis through MID1IP1." (PMID 37110707, 2023). "MID1-interacting protein 1 (MID1IP1) is highly expressed across various cancer types, with its involvement in cancer cell growth and apoptosis evidenced by its association with c-Myc-mediated ribosomal proteins L5, L11, and CNOT2." (PMID 40142004, 2025). "Our studies reveal a new mechanism for its anti-cancer drug role in inhibiting c-Myc via CNOT2 or MID1IP1." (PMID 36233202, 2022). "Our previous study showed that CNOT2 is related to MID1IP1 in regulating the expression of c-Myc and inducing apoptosis in cancer cells." (PMID 36233202, 2022). "Additionally, MID1IP1 contributes to cancer cell growth and death through co-localization with c-Myc-mediated ribosomal proteins L5, L11, and CNOT2." (PMID 38139419, 2023). "Furthermore, previous studies have shown that MID1IP1 regulates cancer cell growth through c-Myc regulation." (PMID 36233202, 2022). "MID1IP1 was highly expressed in HepG2 cells better than 3T3-L1 and other cancer cell lines." (PMID 30700011, 2019). "Additionally, utilizing compounds derived from natural products to target specific oncogenes such as c-Myc, CCR4-NOT transcription complex subunit 2 (CNOT2) and MID1-interacting protein 1 (MID1IP1) have been proposed as an innovative treatment for various cancers, particularly CRC." (PMID 38139419, 2023). "MID1IP1, which induces apoptosis and is controlled by CNOT2, regulates c-Myc via ribosomal proteins L5 and L11, and is involved in cancer cell growth." (PMID 38139419, 2023). "MID1IP1, also known as MIG12, is highly expressed in various cancer types." (PMID 38139419, 2023). "However, further study is required to evaluate the pivotal roles and protein–protein interaction (PPI) of MID1IP1 and CNOT2 in cancers via the Warburg effect in vitro and in vivo." (PMID 32316188, 2020). "CRY1 has been implicated as a prognostic marker progression and survival in CLL and other types of cancer, however, the role of URAHP, MID1IP1, and CLEC3B has not been explored in CLL." (PMID 34187466, 2021).
tumor (4 papers, 2020 to 2025). "The upregulation of RPL5 or RPL11 is regulated through the depletion of MID1IP1, and the depletion of RPL5 and RPL11 activates c-Myc in MID1IP1-depleted HepG2 and Huh7 cells, suggesting that RPL5 and RPL11 are responsible for the regulation of c-Myc as tumor suppressors." (PMID 40864769, 2025).
MID1IP1 also shares sentences with these, for which no sentence is quoted: Alzheimer disease (1 paper); atherosclerosis (1); breast carcinoma (1); hyperlipidemia (1).